SWT1 (SWT1 RNA endoribonuclease homolog)
Synonyms: C1orf26; FLJ20121; HsSwt1
Tractability: PROTAC: ubiquitination databases record sites on it.
Gene: Protein-coding gene on chromosome 1 (185,156,103 to 185,291,983, forward strand). Ensembl gene ENSG00000116668.
Subcellular location (Human Protein Atlas): Cytosol
Gene Ontology:
Cellular component: nucleus
Genetic constraint (gnomAD): Loss-of-function variants: 13 observed, 46.11 expected, observed/expected ratio (o/e) 0.28, 90% interval 0.18 to 0.45. The upper end of that interval is the gene's LOEUF score, 0.45, which puts it in group 1 of 6, group 1 being the genes least tolerant of losing a copy. Missense variants: 501 observed, 568.36 expected, observed/expected ratio (o/e) 0.88, 90% interval 0.82 to 0.95. Synonymous variants: 188 observed, 188.98 expected, observed/expected ratio (o/e) 0.99, 90% interval 0.88 to 1.12.
Homologues: Orthologues: chimpanzee SWT1 (99% identical), macaque SWT1 (95% identical), pig SWT1 (81% identical), dog SWT1 (80% identical), rat Swt1 (74% identical), mouse Swt1 (70% identical), guinea pig SWT1 (70% identical), rabbit SWT1 (67% identical), zebrafish swt1 (27% identical), Drosophila melanogaster Swt1 (10% identical), Caenorhabditis elegans ZK1248.15 (10% identical).
Diseases named in the same sentence as SWT1 in open-access papers:
SWT1 is named in the same sentence as 4 diseases in open-access papers, as found by Europe PMC text mining. Sharing a sentence is not in itself a finding about the gene and the disease.
SWT1 shares sentences with these, for which no sentence is quoted: kidney sarcoma (1 paper); leukemia (1); sarcopenia (1); tumor (1).